RPUSD2 (RNA pseudouridine synthase domain containing 2)
Description:
Pseudouridine synthase that catalyzes pseudouridylation of mRNAs. In addition, it catalyzes the formation of pseudouridine mainly at positions 31 and 32 in the anticodon loop of cytosolic and mitochondrial tRNAs, and at position 34 of certain cytosolic tRNAs such as tRNA(Ile).
Synonyms: C15orf19; C18B11; FLJ31409; PUS9
Tractability: PROTAC: ubiquitination databases record sites on it; its protein half-life has been measured.
Gene: Protein-coding gene on chromosome 15 (40,569,299 to 40,575,171, forward strand). Ensembl gene ENSG00000166133.
Subcellular location (Human Protein Atlas): Microtubules; Nucleoplasm
Gene Ontology:
Molecular function: pseudouridine synthase activity; RNA binding; tRNA pseudouridine synthase activity; tRNA pseudouridine(31) synthase activity; tRNA pseudouridine(32) synthase activity
Biological process: mRNA pseudouridine synthesis; tRNA pseudouridine synthesis; enzyme-directed rRNA pseudouridine synthesis; pseudouridine synthesis; RNA modification
Genetic constraint (gnomAD): Loss-of-function variants: 27 observed, 35.37 expected, observed/expected ratio (o/e) 0.76, 90% interval 0.56 to 1.05. The upper end of that interval is the gene's LOEUF score, 1.05, which puts it in group 4 of 6, group 1 being the genes least tolerant of losing a copy. Missense variants: 570 observed, 580.35 expected, observed/expected ratio (o/e) 0.98, 90% interval 0.92 to 1.05. Synonymous variants: 226 observed, 228.24 expected, observed/expected ratio (o/e) 0.99, 90% interval 0.89 to 1.11.
Homologues: Orthologues: chimpanzee RPUSD2 (99% identical), macaque RPUSD2 (94% identical), dog RPUSD2 (85% identical), pig RPUSD2 (84% identical), rabbit RPUSD2 (84% identical), guinea pig RPUSD2 (82% identical), mouse Rpusd2 (78% identical), rat Rpusd2 (77% identical), tropical clawed frog rpusd2 (56% identical), zebrafish rpusd2 (51% identical), Drosophila melanogaster RluA-1 (42% identical), Drosophila melanogaster RluA-2 (39% identical), and 1 more. Paralogues in human: RPUSD4 (16% identical), RPUSD1 (12% identical), RPUSD3 (12% identical).
Diseases named in the same sentence as RPUSD2 in open-access papers:
RPUSD2 is named in the same sentence as 12 diseases in open-access papers, as found by Europe PMC text mining. Sharing a sentence is not in itself a finding about the gene and the disease. The quoted sentences say what the papers report.
colorectal cancer (2 papers, 2025). A primary or metastatic malignant neoplasm that affects the colon or rectum. "RPUSD2, an RNA-modifying pseudouridine synthase, has sparse research linking it to colorectal cancer metastasis and hepatocellular carcinoma." (PMID 41394823, 2025). "Consistent with findings in breast and colorectal cancer, we observed increased expression of PUS1, MARS, and RPUSD2 in the SCAN-B cohort." (PMID 40918643, 2025).
breast carcinoma (1 paper, 2025). "The elevated expression of PUS1, RPUSD2, and MARS in breast cancer cases showed a positive correlation with high Ki67 levels (FC: 1.35, 1.04, and 1.41, respectively), suggesting their contributing role in tumor growth." (PMID 40918643, 2025).
colon cancer (1 paper, 2023). "The rest three genes KTI12, MAPKAPK3, and RPUSD2 haven’t been well-studied in colon cancer." (PMID 37701039, 2023).
Sepsis (1 paper, 2023). Sepsis is defined as life-threatening organ dysfunction caused by a dysregulated host response to infection. "For instance, genes mediating RNA Ψ modification (TRUB1, TRUB2, PUS1, RPUSD3, RPUSD4, PUS7, RPUSD2) were mainly suppressed in sepsis." (PMID 37701433, 2023).
Viral infection (1 paper, 2021). "Viral infection affected host factors that regulate pseudouridine modification, downregulating DKC1 (also called Cbf5), PUS1, PUS3, and RPUSD2 (also called PUS9), as shown in one of six transcriptome experiments, each." (PMID 34502037, 2021).
cancer (2 papers, 2021 to 2025). A tumor composed of atypical neoplastic, often pleomorphic cells that invade other tissues. "However, the role of RPUSD2 in cancer progression remains unexplored." (PMID 40918643, 2025).
neurological disease (1 paper, 2021). "The single gene associated with this DMR, RNA Pseudouridine Synthase Domain Containing 2 (RPUSD2), is a protein coding gene without reported functional correlates to neurological disease." (PMID 33674671, 2021).
RPUSD2 also shares sentences with these, for which no sentence is quoted: hepatocellular carcinoma (1 paper); infection (1); prostate adenocarcinoma (1); tumor (1); Zinc deficiency (1).